TEKT2 (tektin 2)
Description:
Microtubule inner protein (MIP) part of the dynein-decorated doublet microtubules (DMTs) in cilia and flagellar axoneme. Plays a key role in the assembly or attachment of the inner dynein arm to microtubules in sperm flagella and tracheal cilia. Forms filamentous polymers in the walls of ciliary and flagellar microtubules.
Synonyms: TEKTB1; TEKTIN-T; h-tektin-t
Tractability: Small molecule: a structure with a bound ligand is known. PROTAC: UniProt records ubiquitination sites on it.
Gene: Protein-coding gene on chromosome 1 (36,084,094 to 36,088,278, forward strand). Ensembl gene ENSG00000092850.
Subcellular location: Cytoplasm, cytoskeleton, cilium axoneme; Cytoplasm, cytoskeleton, flagellum axoneme; Cytoplasm, cytoskeleton, microtubule organizing center
Subcellular location (Human Protein Atlas): Connecting piece; Flagellar centriole; Mid piece; Principal piece
Gene Ontology:
Biological process: cilium assembly; cilium movement involved in cell motility; flagellated sperm motility
Cellular component: axonemal microtubule; centriole; nucleus; sperm head-tail coupling apparatus; sperm midpiece; sperm principal piece; axonemal A tubule inner sheath; microtubule cytoskeleton; microtubule organizing center; sperm flagellum; axoneme; cilium; cytoplasm
Genetic constraint (gnomAD): Loss-of-function variants: 45 observed, 52.44 expected, observed/expected ratio (o/e) 0.86, 90% interval 0.68 to 1.1. The upper end of that interval is the gene's LOEUF score, 1.1, which puts it in group 4 of 6, group 1 being the genes least tolerant of losing a copy. Missense variants: 523 observed, 578.05 expected, observed/expected ratio (o/e) 0.9, 90% interval 0.84 to 0.97. Synonymous variants: 202 observed, 236.2 expected, observed/expected ratio (o/e) 0.86, 90% interval 0.76 to 0.96.
Homologues: Orthologues: chimpanzee TEKT2 (99% identical), macaque TEKT2 (97% identical), pig TEKT2 (92% identical), rabbit TEKT2 (92% identical), guinea pig TEKT2 (91% identical), rat Tekt2 (84% identical), mouse Tekt2 (84% identical), tropical clawed frog tekt2 (69% identical), dog ADPRS (52% identical), zebrafish tekt2 (49% identical), Drosophila melanogaster CG3085 (30% identical). Paralogues in human: TEKT1 (32% identical), TEKT3 (29% identical), TEKT4 (29% identical), TEKT5 (28% identical), MAFIP (7% identical).
Diseases named in the same sentence as TEKT2 in open-access papers:
TEKT2 is named in the same sentence as 11 diseases in open-access papers, as found by Europe PMC text mining. Sharing a sentence is not in itself a finding about the gene and the disease. The quoted sentences say what the papers report.
Azoospermia (2 papers, 2023 to 2025). Absence of any measurable level of sperm,whereby spermatozoa cannot be observed even after centrifugation of the semen pellet. "The regulatory network of TF-miRNA-mRNA and lncRNA-miRNA-mRNA was predicted and revealed that has-miR-3127-5p and has-miR-3184-5p might be the regulator of PRM2、FSCN3 and TEKT2 and play a critical role in azoospermia and TGCT." (PMID 37891374, 2023). "Another study reported that Tekt2 was significantly downregulated in nonobstructive azoospermia." (PMID 39949046, 2025).
cervical cancer (2 papers, 2021 to 2023). A primary or metastatic malignant neoplasm involving the cervix. "Two genes, TEKT2 and RPGR, were associated with lymph node metastasis and prognosis in cervical cancer, and were used to construct a lymph node metastasis-related predictive signature." (PMID 37427104, 2023). "Then, we constructed a risk score model based on LPIN2, TEKT2, CXCL2, and FABP4, which had high accuracy in predicting the prognosis of cervical cancer patients." (PMID 34789197, 2021). "TEKT2 knockdown inhibited cervical cancer cell proliferation and migration but promoted apoptosis." (PMID 37427104, 2023). "TEKT2 and RPGR have been found to be associated with lymph node metastasis in cervical cancer." (PMID 37427104, 2023). "Therefore, we speculated that TEKT2 may regulate cervical cancer by affecting cytoskeleton in cervical cancer cells, which needs further study in the future." (PMID 34789197, 2021). "The expression of TEKT2 and RPGR was significantly downregulated in cervical cancer tissues, especially in lymph node metastatic tissues." (PMID 37427104, 2023). "To clarify the role of TEKT2 and RPGR in cervical cancer, we investigated TEKT2 and RPGR expression in seven cervical cancer tissues and three normal cervical tissues." (PMID 37427104, 2023). "The expression of TEKT2 and RPGR was significantly downregulated in cervical cancer tissues, especially in metastatic lymph node tissues." (PMID 37427104, 2023). "Analysis of the Human Protein Atlas data revealed that TEKT2 and RPGR protein levels were also downregulated in cervical cancer samples." (PMID 37427104, 2023). "Furthermore, the sensitivity of patients to chemotherapy drugs was estimated based on the predictive signature and the expression of TEKT2 and RPGR was investigated in the cervical cancer tissue samples." (PMID 37427104, 2023).
Infertility (2 papers, 2021). "On the other hand, TEKT2 participates in microtubules formation, playing a critical role in flagella formation and development; mutations in the TEKT2 gene affect spermatozoa motility and lead to infertility." (PMID 34639209, 2021). "Furthermore, we made the validation of hub-gene (A total of 12 genes were identified as hub genes in testicular carcinoma) in male infertility by GSE4797, 145467, 108886 and 6872 and found TEKT2 and KIF2C might work in infertility." (PMID 34591790, 2021).
male infertility (2 papers, 2021 to 2023). The inability of the male to effect fertilization of an ovum after a specified period of unprotected intercourse. "Among them, miRNAs (has-miR-3127-5p and has-miR-3184-5p), lncRNAs (AL356488.2 and AL645608.3) and TFs (NANOG and HEY1) as the key regulatory factors of PRM2, FSCN3 and TEKT2, were predicted significantly associated with male infertility." (PMID 37891374, 2023).
lymph node metastasis (1 paper, 2023). "In summary, we constructed a lymph node metastasis-related predictive signature based on TEKT2 and RPGR expression to predict the prognosis, immune infiltration, and efficiency of individualized therapeutic agents." (PMID 37427104, 2023). "TEKT2, RPGR, and the risk score of the lymph node metastasis-related prediction signature were significantly correlated with checkpoint genes." (PMID 37427104, 2023).
testicular germ cell tumor (1 paper, 2023). A germ cell tumor arising from the testis. "Three of them (PRM2, FSCN3 and TEKT2) were significantly down-regulated in the testicular germ cell tumors and their methylation levels were associated with the pathogenesis." (PMID 37891374, 2023).
cancer (1 paper, 2014). A tumor composed of atypical neoplastic, often pleomorphic cells that invade other tissues. "Interestingly only 6 genes including CCDC19, MMP1, SLC family, TEKT2, WDR family and ZMYND10 had been reported relevant to cancer survival in a separate study (where a total of 88 genes were reported,)." (PMID 25551281, 2014).
tumor (1 paper, 2023). "RT-qPCR results revealed that the mRNA expression of TEKT2 and RPGR was significantly downregulated in tumor samples, especially in metastatic lymph node samples." (PMID 37427104, 2023).
TEKT2 also shares sentences with these, for which no sentence is quoted: asthenospermia (1 paper); retinal degeneration (1); retinal disease (1).